HYKK (hydroxylysine kinase)
Description:
Catalyzes the GTP-dependent phosphorylation of 5-hydroxy-L-lysine.
Synonyms: AGPHD1; LOC123688
Tractability: PROTAC: ubiquitination databases record sites on it.
Gene: Protein-coding gene on chromosome 15 (78,507,564 to 78,537,372, forward strand). Ensembl gene ENSG00000188266.
Subcellular location: Cytoplasm
Subcellular location (Human Protein Atlas): Aggresome; Cytosol; Nucleoplasm; Vesicles
Pathways (Reactome):
Metabolism: Lysine catabolism
Gene Ontology:
Molecular function: hydroxylysine kinase activity; amino acid kinase activity
Biological process: L-lysine catabolic process
Cellular component: mitochondrial matrix; cytoplasm
Genetic constraint (gnomAD): Loss-of-function variants: 16 observed, 25.57 expected, observed/expected ratio (o/e) 0.63, 90% interval 0.42 to 0.95. The upper end of that interval is the gene's LOEUF score, 0.95, which puts it in group 4 of 6, group 1 being the genes least tolerant of losing a copy. Missense variants: 329 observed, 401.41 expected, observed/expected ratio (o/e) 0.82, 90% interval 0.75 to 0.9. Synonymous variants: 136 observed, 141.44 expected, observed/expected ratio (o/e) 0.96, 90% interval 0.84 to 1.11.
Gene-disease validity (ClinGen):
ClinGen rates the evidence that HYKK causes each of these diseases.
inborn disorder of lysine and hydroxylysine metabolism (inheritance undetermined): No Known Disease Relationship.
Homologues: Orthologues: chimpanzee HYKK (99% identical), macaque HYKK (96% identical), pig HYKK (85% identical), rat Hykk (83% identical), guinea pig HYKK (80% identical), mouse Hykk (80% identical), rabbit HYKK (76% identical), dog HYKK (75% identical), tropical clawed frog hykk (53% identical), zebrafish hykk.2 (45% identical), zebrafish hykk.1 (42% identical), Drosophila melanogaster CG31751 (31% identical).
Diseases named in the same sentence as HYKK in open-access papers:
HYKK is named in the same sentence as 10 diseases in open-access papers, as found by Europe PMC text mining. Sharing a sentence is not in itself a finding about the gene and the disease. The quoted sentences say what the papers report.
lung carcinoma (10 papers, 2011 to 2025). "However, multiple meta-analyses have shown that the rs8034191 variant in the HYKK (AGPHD1) gene is a risk factor for lung cancer, with individuals carrying the HYKK (AGPHD1) rs8034191 (A > G) variant having a higher likelihood of developing lung cancer." (PMID 38834983, 2024). "It is an intron variant in HYKK and has previously been associated with lung cancer and smoking behavior, which may indicate the basis for its ability to classify pneumonia, and not an inherent increased risk to infection." (PMID 39008506, 2024). "This suggests that HYKK (AGPHD1) is a promising candidate gene for further investigation into its role as a potential causal factor in multiple subtypes of lung cancer, particularly in lung squamous cell carcinoma, based on the high degree of colocalization likelihood observed." (PMID 38834983, 2024). "However, in the replication cohort, only three genes were found to have such a causal association with lung cancer and its subtypes, and of these, HYKK (also known as AGPHD1) was consistently present in both the primary analysis dataset and the replication cohort." (PMID 38834983, 2024). "In addition, because rs649530917,18 in CHRNB4 and rs80341912,17 in HYKK had been reported to exhibit the strongest association with lung cancer risk in CHRNB4 and HYKK, separately, we also explored the effect of rs6495309 and rs8034191 on whole-genome gene expression level." (PMID 30104567, 2018). "PheWAS confirmed chromosome 15 SNPs as jointly associated with respiratory traits and lung cancer, regulating IREB2, CHRNA3/5, HYKK, and PSMA4." (PMID 41377765, 2025). "Qi Wang discovered that the HYKK (AGPHD1) gene interacts with the CHRNA5-CHRNA3-CHRNB4 cluster and is implicated in the risk of lung cancer development." (PMID 38834983, 2024). "In the results of the SMR analysis, we discovered that HYKK (AGPHD1) was consistently identified in lung cancer data from both TRICL and ILCCO studies, and it was replicated specifically in non-small cell lung cancer, lung adenocarcinoma, and lung squamous cell carcinoma within the FinnGen dataset." (PMID 38834983, 2024). "We also evaluated whether the functional eQTL analysis identified the same lung cancer-related pathways after removing the HYKK and CHRNB4, which were eQTL related pathways of genes underlying rs16969968, rs6495309, and rs8034191." (PMID 30104567, 2018).
lung squamous cell carcinoma (1 paper, 2024). "Following HEIDI tests and colocalization analyses, it was revealed that HYKK (AGPHD1) is associated with an increased risk of squamous cell carcinoma of the lung, with an odds ratio and confidence interval of OR = 1.28,95%CI = 1.24 to 1.33." (PMID 38834983, 2024). "Lastly, by leveraging comprehensive gene expression datasets, we adopted a stringent selection process to evaluate actionable drug targets and uncovered HYKK (AGPHD1) as a treatment target associated with the risk of lung squamous cell carcinoma." (PMID 38834983, 2024). "In our research, we found that rs931794 in the HYKK (AGPHD1) gene is a risk factor for lung squamous cell carcinoma." (PMID 38834983, 2024). "The results showed that HYKK (AGPHD1) was associated with an increased risk of lung squamous cell carcinoma in the primary analysis set (OR: 1.28; 95% CI: 1.24–1.33), which is consistent with the results in the replication queue (OR: 1.34; 95% CI: 1.24–1.44)." (PMID 38834983, 2024). "After combining the results of different methods, we finally found a potential causal association between HYKK (AGPHD1) and lung squamous cell carcinoma." (PMID 38834983, 2024). "In conclusion, our MR analysis revealed a relationship between the HYKK (AGPHD1) gene and the risk of developing lung squamous cell carcinoma, consistent with prior randomized controlled trials and meta-analysis studies." (PMID 38834983, 2024). "We propose that HYKK (AGPHD1) may function as a disease-causing gene specifically for lung squamous cell carcinoma, although the exact physiological role of HYKK (AGPHD1) remains unclear." (PMID 38834983, 2024). "We have found that the HYKK (AGPHD1) gene is associated with an increased risk of squamous cell carcinoma of the lung, suggesting that this gene may represent a potential therapeutic target for both the prevention and treatment of lung squamous cell carcinoma." (PMID 38834983, 2024). "Similarly, HYKK (AGPHD1) may also potentially influence the risk of developing lung squamous cell carcinoma through this same pathway." (PMID 38834983, 2024). "Our study identified hydroxylysine kinase (HYKK), also known as amino-glycoside phosphotransferase 1 (AGPHD1), as a potentially causally related druggable target gene for squamous cell carcinoma of the lung." (PMID 38834983, 2024).
HYKK also shares sentences with these, for which no sentence is quoted: adenocarcinoma (1 paper); emphysema (1); infection (1); intracranial aneurysm (1); lung adenocarcinoma (1); melanoma (1); non-small cell lung carcinoma (1); pneumonia (1).